MYLK (myosin light chain kinase)
Diseases named in the same sentence as MYLK in open-access papers (continued):
Sharing a sentence is not in itself a finding about the gene and the disease.
osteoporosis (1 paper, 2021). A condition of reduced bone mass, with decreased cortical thickness and a decrease in the number and size of the trabeculae of cancellous bone (but normal chemical composition), resulting in increased fracture incidence. "Our study showed that women with homozygous MYLK rs12163585 major alleles had an increased risk of osteoporosis following ovariectomy compared to those with minor alleles." (PMID 33800915, 2021). "Our results show the correlation between the MYLK gene and ovariectomy and demonstrate that the risk of osteoporosis in women who underwent ovariectomy was significantly higher and nearly double the risk of those without." (PMID 33800915, 2021). "Analysis of the differences in the risk of osteoporosis and ovariectomy in the MYLK rs12163585 and PTGS1 rs1213265 genotypes showed significant associations with each genotype." (PMID 33800915, 2021). "In this prospective GWAS, we identified an association between MYLK rs12163585 and PTGS1 rs1213265 variants, ovariectomy, and the risk of osteoporosis using HEXA Korean women data." (PMID 33800915, 2021).
pancreatic adenocarcinoma (1 paper, 2022). "Furthermore, survival analysis of these genes was conducted with the Kaplan-Meier method, and as a result, MYLK, SOCS3, STAT5B, and PLAU genes were obtained with the highest mortality rate for pancreatic adenocarcinoma (PAAD) patients." (PMID 35928368, 2022).
pancreatic cancer (1 paper, 2024). "MYLK inhibitors can block the invasion and adhesion of human pancreatic cancer cell lines, suggesting that targeting MYLK may be a promising therapeutic strategy for PC cell invasion and metastasis prevention." (PMID 39129004, 2024). "The Spearman correlation analysis showed AGTPBP1 was positively correlated with the expression of MYLK and MAP1A in pancreatic cancer tissues by GEPIA analysis." (PMID 39129004, 2024). "According to the GEPIA analysis based on TCGA, similar to AGTPBP1, the expression of MYLK and MAP1A in pancreatic cancer tissues was significantly upregulated (P < 0.05)." (PMID 39129004, 2024). "Currently, research is focused on MYLK in human malignancies, including digestive system tumors and those outside the digestive tract, not just pancreatic cancer." (PMID 39129004, 2024).
parasitic infection (1 paper, 2023). "In Giardia duodenalis, cysteine proteases play a role in the pathophysiology of parasitic infection by inducing the degradation and redistribution of the intestinal epithelial cytoskeletal protein villin via myosin light chain kinase." (PMID 37008342, 2023).
Patent ductus arteriosus (1 paper, 2024). In utero, the ductus arteriosus (DA) serves to divert ventricular output away from the lungs and toward the placenta by connecting the main pulmonary artery to the descending aorta. "Various genes, including ACTA2, MYH11, MYLK, and PRKG1, have been identified to be responsible for hereditary non-syndromic TAAD, which is typically accompanied by patent ductus arteriosus (TAAD/PDA)." (PMID 38773466, 2024).
prostate tumors (1 paper, 2008). "Due to the central role played by the cytoskeleton in cell division and motility, it has been demonstrated that MYLK inhibition induces apoptosis in mammary prostate cancer cells and inhibits the growth of mammary and prostate tumors in rats and mice." (PMID 19055846, 2008).
rectal cancer (1 paper, 2025). A primary or metastatic malignant neoplasm that affects the rectum. "In this study, we identified four molecular markers (MYLK, FLNC, MYH11, and NEXN) as potential prognostic biomarkers for rectal cancer for the first time." (PMID 39762799, 2025).
sarcoma (1 paper, 2017). A usually aggressive malignant neoplasm of the soft tissue or bone. "Moreover, the detection by RT-PCR of specific sarcoma genes like ARSG,MYLK, and NBEA confirmed our assumption, even though the level of expression of ARSGand MYLK were lower than that of mouse sarcoma WEHI-164 cell line used as positivecontrol." (PMID 28430664, 2017).
serous ovarian cancer (1 paper, 2022). "Thereafter, we examined if the expression levels of SIK2 and MYLK‐pS343 were associated with overall survival of FIGO stage III‐IV serous ovarian cancer patients." (PMID 35278271, 2022).
cancer (67 papers, 2007 to 2026). A tumor composed of atypical neoplastic, often pleomorphic cells that invade other tissues. "In our discovery analysis, we found rs3796164 as the most strongly associated variant for CVD and cancer, which is annotated close to the MYLK gene." (PMID 33531528, 2021). "MYLK encodes the multi-functional myosin light chain kinase (MLCK) which is involved in diverse functions in multiple types of cancer." (PMID 30161129, 2018). "We previously demonstrated that genes influenced by MYLK expression are associated with a poor prognosis in a variety of cancer." (PMID 30161129, 2018). "Importantly, we identified that cancer cell-derived MAMDC2 promotes MYLK expression in cancer-associated fibroblasts (CAFs) through paracrine signaling." (PMID 40427044, 2025). "Additionally, COL1 A1, COL1 A2, and MYLK are markers of fibroblasts (myofibroblasts), which indicates that MSCs may also be reprogrammed by tumor cells into cancer-associated fibroblasts (CAFs), further assisting in malignant progression." (PMID 40524208, 2025). "In silico knockout of MYLK produced regulatory shifts enriched for tight junction organization, endothelial apoptosis, angiogenesis, vascular permeability, and vascular/cancer-related pathways." (PMID 41993190, 2026). "The results indicated that seven risk genes (SERPINE1, LAMC2, MYLK, IL21R, KRT81, MAMDC2, and PAEP) of the signature were differentially expressed in the cancer tissues compared to the normal tissues." (PMID 37636564, 2023). "Among the 102 feature genes, eight genes (MYLK, GADD45A, ACADM, UQCR11, TST, PTCD3, SOD1, CD151) were significantly enriched in the cancer hallmark of adipogenesis." (PMID 36905391, 2023). "Circular RNA (circRNA) myosin light chain kinase (circMYLK) has recently received increasing attention in cancer biology." (PMID 35701309, 2022). "CircMYLK is derived from exons 25–29 of myosin light chain kinase (MYLK), and has been reported to be an oncogenic factor in several cancer types." (PMID 36142352, 2022). "Previous research has linked aberrant expression of HS3ST3A1, AQP9, MYLK, and RAB23 to cancer formation, invasion, and prognosis." (PMID 36199571, 2022). "Myosin light chain kinase (MYLK) can catalyze the phosphorylation of the myosin light chain and regulate the invasion and metastasis of some malignant tumors." (PMID 36110205, 2022). "SIK2 protein expression was positively correlated with the expression of MYL2‐pS19 (r = 0.87; Pearson correlation coefficient, P = 0.01) and MYLK‐pS343 (r = 0.83, Pearson correlation coefficient, P = 0.02) in these cancer cell lines." (PMID 35278271, 2022). "Mechanistically, SIK2 regulated cancer cell motility and migration by myosin light chain kinase, smooth muscle (MYLK)‐meditated phosphorylation of myosin light chain 2 (MYL2)." (PMID 35278271, 2022). "Here the authors show that a high molecular weight form of myosin light chain kinase, MLCK210, is required for myeloid cell integrin α4β1 activation and adhesion and that MLCK210 inhibition reduces tumor growth and inflammation in preclinical cancer models." (PMID 35365657, 2022). "Prior studies have shown that MYLK can phosphorylate MLC and that suppression of MLC phosphorylation causes failure of cytokinesis and results in multipolarity in cancer cells." (PMID 33980265, 2021). "Cytoskeletal myosin II phosphorylated by MYLK increases the metastatic potential of tumor cells, and MYLK-dependent cytoskeleton rearrangement adjusts the angiogenesis of the vascular endothelial barrier, which is an inevitable step in cancer metastasis." (PMID 33980265, 2021). "Myosin light chain kinase (MYLK) catalyzes the phosphorylation of myosin light chain and regulates the invasion and metastasis of some malignant tumors." (PMID 32547947, 2020). "EGFR, IGF1R, LAMA2, MYLK, PIK3CA, PIK3R1, and MYLK are members of the focal adhesion pathway, whose dynamics are highly altered in cancer cells." (PMID 31024613, 2019).
cancer (continued). "We now show that MYLKP1 selectively transcribes mRNA in cancer cells and dramatically decreases the expression of the functional MYLK." (PMID 30161129, 2018). "Previously, we have shown that an upregulation in MYLKP1 mRNA expression produces a functional transcript in multiple cancer cell lines, and this corresponds with the downregulation of functional MYLK mRNA in cancer cell lines." (PMID 30161129, 2018). "We have previously shown MYLKP1 expression in cancer cell lines inhibits the expression of MYLK in cancer cells." (PMID 30161129, 2018). "MYLK is responsible for the high proliferative ability of cancer cells through anti-apoptosis in which the p38 pathway is involved and represents a mediator of invasive behavior of cancer cells that are regulated by the ZEB1/miR-200 feedback loop." (PMID 29301256, 2018). "MYLK is involved in tumor metastasis, when cytokines stimulate the cell surface receptors in tumors, and its mRNA expression in cancer patients with recurrence and distant metastasis was higher than those in the early stage of cancer." (PMID 28811522, 2017). "TKS5 and MYLK represent two effectors/mediators of the invasive behavior of cancer cells that are regulated by the ZEB1/miR-200 feedback loop." (PMID 26334100, 2015). "Taken together, these data underline the relevance of ZEB1/miR-200c regulating MYLK and TKS5 expression in a wide panel of cancer cell lines." (PMID 26334100, 2015). "In some publications MYLK was shown to be essential for invasion as well as for migration via MLC2 phosphorylation dependent Myosin II activation in cancer cells." (PMID 26334100, 2015). "In summary, TKS5 and MYLK represent two mediators of invasive behavior of cancer cells that are regulated by the ZEB1/miR-200 feedback loop." (PMID 26334100, 2015). "As a result, some reports described the use of MYLK inhibitors as anti-cancer agents since they prevent cancer cells migration." (PMID 19055846, 2008). "However, various other studies related to MYLK and other cancers such as bladder, cervical, prostate, and hepatocarcinoma showed that MYLK increases the invasion and migration of cancer cells to other organs in the body." (PMID 35928368, 2022). "Although the CLIC1 role in ccRCC has not been fully elucidated, several primary cell lines from ccRCC patients indicated that CLIC1 inhibition blocked the myosin light chain kinase (MYLK) and β3 integrin, decreasing tumor proliferation and slowing cancer progression." (PMID 33920158, 2021). "In addition, higher S100A4 expression was observed in various cancer types compared to MYLK, BDNF, and PCOLCE2." (PMID 31581665, 2019). "Additionally, in the NCI60 panel, which comprises cell lines from nine different cancer entities, we observed clear inverse correlations of expression between miR-200c and MYLK/TKS5." (PMID 26334100, 2015). "Cancer cell proliferation and migration require rapid dynamic regulation of the cytoskeleton, which is controlled by series of cytoskeleton regulatory proteins, in which myosin light chain kinase (MLCK) is a critical participant." (PMID 24714365, 2014). "Furthermore, since MLC20 phosphorylation is necessary for cell motility, MYLK inhibition blocks cancer cell invasion and adhesion in vitro." (PMID 19055846, 2008). "NETs awakened cancer cells and there was concomitant remodeling of laminin, which was sequentially cleaved by two NET-associated proteases, NE and MMP-9, through the activity of integrin α3β1 and focal adhesion kinase/ERK/myosin light chain kinase/yes-associated protein (FAK/ERK/MLCK/YAP) signaling." (PMID 34758877, 2021). "However, we could show that knockdown of either MYLK or TKS5 significantly impaired cancer cell invasion, thereby phenocopying at least partly the effect of miR-200c overexpression." (PMID 26334100, 2015). "Therefore, we investigated whether individual knockdown of MYLK or TKS5 can phenocopy the effects of miR-200c overexpression on cancer cell migration and invasion." (PMID 26334100, 2015).
cancer (continued). "Then, to finalize the genes and protein products in question, we evaluated the crucial genes in the GEPIA database and finally confirmed MYLK, SOCS3, STAT5B, BIRC5, PLK1, and RAPGAP1 proteins significantly in this cancer database." (PMID 35928368, 2022). "Cancer cells co‐cultured with adipocytes also showed increased SIK2 phosphorylation at S358, and increased expression of SIK2, MYL2‐pS19 and MYLK‐pS343." (PMID 35278271, 2022). "The potential for cross-talk between the parent gene and the pseudogene (MYLK and MYLKP1) and nmMLCK's potential as a cancer biomarker provide unique targets for cancer therapeutics that have the potential to affect cancer cell proliferation." (PMID 30161129, 2018). "To assess the regulation of MYLK and TKS5, we performed correlation analyses in several datasets derived from human cancer cell lines." (PMID 26334100, 2015). "The genes preferentially mutated in metastases were MYLK, PEAK1, SLC2A4RG, EVC2, XIRP2, PALB2, and ESR1 (five of which are not significantly mutated in any type of human primary cancer)." (PMID 34771579, 2021). "We could show that MYLK and TKS5 are indeed direct mir-200c target genes, which expression patterns correlate positively with that of ZEB1 in different datasets of cancer cell lines." (PMID 26334100, 2015). "The multifunctional non-muscle isoform of myosin light chain kinase (nmMLCK) is critical to the rapid dynamic coordination of the cytoskeleton involved in cancer cell proliferation and migration." (PMID 24714365, 2014). "The eight IA genes we identified are associated with cellular cytoskeleton, cell invasion and oncogenetic signaling, including the well-known cancer driver EGFR, and FAK-Src signaling (ITGA3, MYLK); ITGA3 (integrin, alpha 3) mediates cell survival and invasion through FAK-Src signaling." (PMID 23590835, 2013). "lncRNA-H19 and circular MYLK as well as circular CTDP1 could regulate the expression of DNMT3B, HAS3, VEGFA and ITGB1 through competing miRNA response elements (MREs) of miRNA-29a-3p, which would result in growth and metastasis of cancer." (PMID 27363013, 2016). "Ca2+/calmodulin-activated kinases, such as myosin light chain kinase (MLCK) and zipper-interacting protein kinase (ZIPK), also promote the phosphorylation of RLC on Ser19 and Thr18, and are increasingly promising therapeutic targets, especially for cancer treatment." (PMID 26542704, 2015). "Most normal cells (HUF, HPAEC, HUVEC, 1° prostate) and non-tumorigenic Beas-2B cells are above while most cancer cells, with the exception of ECC-1 cells, are below the level of MYLK expression in HeLa cells." (PMID 24224004, 2013).
tumor (52 papers, 2007 to 2026). "In endothelial cells, MYLK perturbation altered junction integrity and trans-endothelial tumor cell migration; in LUAD cells, MYLK gain/loss affected migration, invasion, and proliferation." (PMID 41993190, 2026). "Next, we used the TCGA-COAD to analyze the mRNA expression levels of the MYLK in normal and tumor tissues." (PMID 40427044, 2025). "In tumors, MYLK promotes cell migration, invasion, and stromal remodeling, playing an important role in tumor progression and metastasis." (PMID 40427044, 2025). "The MYLK and MYH11 genes encode actin and myosin, which play an important role in the contraction and migration of tumour cells." (PMID 39294858, 2024). "The results showed that MYLK gene and protein expressions were higher in normal tissue than in tumor tissue." (PMID 39596804, 2024). "We had previously highlighted the reduced expression of MYLK in liver metastases relative to normal tissue, while it was expressed at normal levels in primary tumours." (PMID 36077612, 2022). "In contrast, two genes, ADH1B and MYLK, with an established relationship with sCRC, had high levels of downregulation of tumour suppressor mRNAs." (PMID 36077612, 2022). "Aberrant MYLK is related to malignant transformation of normal cells and affects the tumor cell migration and invasion abilities." (PMID 34733825, 2021). "High MYLK expression was positively correlated with HBsAg (P = 0.04), microvascular invasion (P = 0.031), and tumor encapsulation (P = 0.028)." (PMID 34588420, 2021). "Based on these results, we speculate that MAMDC2, as a secreted protein, may be released from tumor cells into the tumor microenvironment, where it regulates MYLK expression in CAFs." (PMID 40427044, 2025). "Our findings suggest that the MAMDC2/MYLK axis may play an important role in tumor stroma interactions and the progression of high-stromal CRC." (PMID 40427044, 2025). "In MCF10A breast epithelial cells, MYLK loss has been evidenced to increase their motility and invasiveness and to activate signals such as ERK, which may promote tumor metastasis." (PMID 37723567, 2023). "Targeting myosin light chain kinase with kinase inhibitors might be an effective strategy to inhibit tumor metastasis." (PMID 33980265, 2021). "ERK could facilitate tumor cell migration via phosphorylating calpain, myosin light chain kinase, paxillin, and focal adhesion kinase." (PMID 32760221, 2020). "Inhibition of either of CYB5R3 or MYLK could be effective at halting tumor progression because the inhibition of one of these genes should modulate the expression of the other." (PMID 24944582, 2014). "Moreover, inhibition of MYLK was reported to induce apoptosis and reduce tumor growth in vivo." (PMID 33255928, 2020). "However, another gene mediating focal adhesion, MYLK, was downregulated in tumor cells." (PMID 17389037, 2007). "Proteins downregulated in KO tumours with roles in regulating adhesion and angiogenesis included EphA2, integrin ITGB5, MCAM, and MYLK (myosin light chain kinase)." (PMID 41226720, 2025). "This subset ultimately acts as a regulator of LCRC aggressiveness, promoting tumor invasion through TGF-β signaling, upregulation of pro-tumor genes (RAMP1, MYLK, MYH11) and activation of muscle-invasive pathways." (PMID 41450739, 2025). "Myeloid cell trafficking to tumours depends on PI3Kγ‐mediated integrin activation, and subsequent myeloid cell recruitment and tumour inflammation depend on PLCγ, CalDAG‐GEFI and II, Rap1a, RIAM, talin, paxillin and myosin light chain kinase." (PMID 40434054, 2025). "In CAFs, 12(S)-HETE-induced MYLK activation enhances CAF contractility and motility, creating favorable conditions for tumor cell invasion." (PMID 40427044, 2025). "HMGB2 in POSTN+ fibroblasts is predicted to bind to PLD2, LRP5, MYLK, and CD44 on tumor cells, regulating downstream genes, including BIRC5, CCNA2, CCNB1, CCNB2, CDC20, and MKI67, which are related to the cell cycle." (PMID 38519500, 2024).